UBE2Q2 (ubiquitin conjugating enzyme E2 Q2)
Description:
Accepts ubiquitin from the E1 complex and catalyzes its covalent attachment to other proteins. In vitro catalyzes 'Lys-48'-linked polyubiquitination.
Synonyms: DKFZp762C143
Tractability: PROTAC: UniProt records ubiquitination sites on it; ubiquitination databases record sites on it.
Gene: Protein-coding gene on chromosome 15 (75,843,307 to 75,901,078, forward strand). Ensembl gene ENSG00000140367.
Subcellular location: Cytoplasm
Pathways (Reactome):
Immune System: Antigen processing: Ubiquitination & Proteasome degradation
Metabolism of proteins: Synthesis of active ubiquitin: roles of E1 and E2 enzymes
Gene Ontology:
Molecular function: protein binding; ubiquitin-protein transferase activity; ubiquitin conjugating enzyme activity
Biological process: protein K48-linked ubiquitination; protein ubiquitination
Cellular component: cytosol; cytoplasm
Genetic constraint (gnomAD): Loss-of-function variants: 34 observed, 35.89 expected, observed/expected ratio (o/e) 0.95, 90% interval 0.72 to 1.26. The upper end of that interval is the gene's LOEUF score, 1.26, which puts it in group 5 of 6, group 1 being the genes least tolerant of losing a copy. Missense variants: 309 observed, 328.2 expected, observed/expected ratio (o/e) 0.94, 90% interval 0.86 to 1.03. Synonymous variants: 116 observed, 119.26 expected, observed/expected ratio (o/e) 0.97, 90% interval 0.84 to 1.13.
Homologues: Orthologues: chimpanzee UBE2Q2 (99% identical), mouse Ube2q2 (96% identical), rat Ube2q2 (96% identical), pig UBE2Q2 (95% identical), guinea pig UBE2Q2 (95% identical), rabbit UBE2Q2 (94% identical), tropical clawed frog ube2q2 (86% identical), zebrafish ube2q2 (85% identical), zebrafish ube2q1 (82% identical). Paralogues in human: UBE2Q1 (75% identical), UBE2QL1 (23% identical), UBE2E3 (17% identical), UBE2E2 (16% identical), UBE2E1 (15% identical), UBE2D2 (13% identical), UBE2D3 (13% identical), UBE2D4 (13% identical), UBE2D1 (12% identical), UBE2L5 (10% identical), UBE2L3 (9% identical), UBE2L6 (8% identical).
Diseases named in the same sentence as UBE2Q2 in open-access papers:
UBE2Q2 is named in the same sentence as 17 diseases in open-access papers, as found by Europe PMC text mining. Sharing a sentence is not in itself a finding about the gene and the disease. The quoted sentences say what the papers report.
gout (2 papers, 2015 to 2025). A condition characterized by painful swelling of the joints, which is caused by deposition of urate crystals. "In the context of gout, it is possible that variants in UBE2Q2 could affect inflammatory signaling or the degradation of proteins involved in urate metabolism." (PMID 41075270, 2025). "Future research could focus on understanding how UBE2Q2 variants influence the balance between pro-inflammatory and anti-inflammatory signals in gout flares." (PMID 41075270, 2025). "As expected, most of the urate loci are also risk factors for gout, with only four loci (INHBB, HNF4G, UBE2Q2, and BCAS3) yet to be formally associated with gout at a nominal level of significance." (PMID 25889045, 2015).
chronic kidney disease (1 paper, 2016). Impairment of the renal function secondary to chronic kidney damage persisting for three or more months. "Another underlined gene, ubiquitin-conjugating enzyme E2Q family member 2 (UBE2Q2), has been identified to have association with chronic kidney disease." (PMID 27980639, 2016).
colorectal cancer (1 paper, 2014). A primary or metastatic malignant neoplasm that affects the colon or rectum. "We sought to investigate the expression levels of the UBE2Q2 gene in colorectal cell lines as well as in cancerous and normal tissues from patients with colorectal cancer." (PMID 24753643, 2014). "Our results showed that all the colorectal carcinoma cell lines tested express UBE2Q2 protein and also its transcript." (PMID 24753643, 2014). "Increased levels of UBE2Q2 immunoreactivity was observed in the 65.11% (28 out of 43) of the colorectal carcinoma tissues when compared with their corresponding normal tissues." (PMID 24753643, 2014). "Overexpression of UBE2Q2 in the majority of the colorectal carcinoma samples denotes that it may have implications for the pathogenesis of colorectal cancer." (PMID 24753643, 2014).
colorectal tumor (1 paper, 2014). "Tissues from the cancerous part of 43 colorectal tumors along with their normal counterparts were subjected to western blot analysis for the UBE2Q2 protein." (PMID 24753643, 2014). "Western blotting was employed to investigate the levels of the UBE2Q2 protein in 8 colorectal cell lines and 43 colorectal tumor samples." (PMID 24753643, 2014).
uremia (1 paper, 2013). A clinical syndrome associated with the retention of renal waste products or uremic toxins in the blood. "However, probe sets of the protein-degradation machinery, e.g. UBE2E1, USP32, UBE2Q2, and UBR3 were inhibited in uremia, indicating that evaluation of the ubiquitin-proteosome machinery requires more detailed investigation." (PMID 23809614, 2013).
tumor (4 papers, 2013 to 2019). "UBE2Q2 expression was assessed in Iranian BC cases, and showed that the majority of tumor tissues had UBE2Q2 over expression compared with their corresponding normal margins." (PMID 31286981, 2019). "The results also showed no significant change between the cancerous and unaffected parts in 23.26% of the tumor specimens as well as the downregulation of the UBE2Q2 protein in the cancerous parts in 11.63% of the cases." (PMID 24753643, 2014). "Interestingly, although no VHL mutation was detected in tumor BC_1R and BC_2L, mutations in UBE2Q2 and PARK2, two genes involved in ubiquitin-mediated proteolysis, were present in these two tumors, respectively." (PMID 27383411, 2016). "Therefore, more marker genes like for example MMP13, UBE2Q2, Nectin-4 or ALDH will have to be tested for their ability not only in tumour cell detection but also in tumour cell characterization." (PMID 24202442, 2013).
cancer (3 papers, 2014). A tumor composed of atypical neoplastic, often pleomorphic cells that invade other tissues. "UBC-25 exhibited high amino acid sequence conservation with UBE2Q2, a metazoan specific UBC implicated in cancer." (PMID 24584095, 2014). "The observations that cancers of several cell origins overexpress UBE2Q2 at both the transcript and protein levels suggested a role in promoting proliferation and/or transformation." (PMID 24584095, 2014). "UBE2Q2, a homologue of this gene, is also up regulated at protein and/ or mRNA levels in different cancers." (PMID 25035859, 2014). "In our previous studies, we characterized the two new members of E2 family, UBE2Q1 and UBE2Q2 genes, and reported their differential expression in some human cancers." (PMID 25035859, 2014). "Moreover, we characterized ubc-25, a gene encoding an E2 ubiquitin-conjugating enzyme whose human ortholog, UBE2Q2, is deregulated in several cancers." (PMID 24584095, 2014). "However, finding the correlation between the product(s) of UBE2Q2 gene and cancer development is a subject of further investigation." (PMID 24753643, 2014).
UBE2Q2 also shares sentences with these, for which no sentence is quoted: acute lymphoblastic leukemia (2 papers); Alzheimer disease (1); breast carcinoma (1); diabetes (1); gastric cancer (1); head and neck squamous cell carcinoma (1); head and neck tumors (1); leukemia (1); Sepsis (1); Type 2 diabetes (1).